IRF3 (interferon regulatory factor 3)
Diseases named in the same sentence as IRF3 in open-access papers (continued):
Sharing a sentence is not in itself a finding about the gene and the disease.
tumor (continued). "This activation leads to IRF3 phosphorylation and production of type I interferons (e.g., IFN-β) and inflammatory cytokines (e.g., CXCL10, IL-6), enhancing the tumor’s immune profile." (PMID 39949780, 2025). "In the tumor microenvironment (TME), PS-positive tumor EVs contribute to inhibition of TLR3-mediated IRF3 and IFN-β expression through binding with CD300a on DCs." (PMID 40507267, 2025). "Our results indicate that genetic ablation of Daxx up-regulated the p-TBK1 and p-IRF3 expression levels to sensitize chemotherapy, suggesting that Daxx is a negative regulator of the STING signal, thereby slowing tumor growth in vivo." (PMID 40296918, 2025). "Subsequently, we detected the phosphorylation levels of TANK‐binding kinase 1 (TBK‐1) and interferon regulate factor 3 (IRF‐3) in CT26, H22, and GL261 cells using phosflow, and the IFN‐β level in tumor cell supernatants and tumor tissues homogenates by ELISA." (PMID 40470716, 2025). "IF and IHC experiments demonstrated a significant increase in the expression of phosphorylated TBK1 (p-TBK1), phosphorylated IRF3 (p-IRF3) and IFN-β within the tumor tissue after combination therapy." (PMID 40355720, 2025). "Both poly-I:C and rintatolimod activate TLR3-mediated nuclear translocation of TRAF3 and IRF3, leading to type-1 interferon production and CXCL10 expression, which attract CD8+ T cells for anti-tumor immunity." (PMID 39949780, 2025). "The TME of NTT tumours, RTTPtgs1/2 KO tumours and RTT IRF3/7 tumours share an inflammatory state, and monocytes are the most abundant cell type in this transcriptional state." (PMID 39604727, 2025). "c-di-GMP inhibits 4T1 cell growth and increases phosphorylation of STING, TBK1, IRF3 and STAT1 and the IFN-β level in tumor-bearing mice." (PMID 40552295, 2025). "While in some tumor cells, enriched cGAS/STING signaling kindles a tumor-promoting function by activating NF-κB, TBK1, and IRF3." (PMID 38474405, 2024). "Depletion of cGAS, STING, IRF3, or IFNα/β receptor 1 (IFNAR1) abolishes this increase, indicating that 5-FU/oxaliplatin mediated upregulation of PD-L1 expression is dependent on tumor cell intrinsic cGAS/STING signaling." (PMID 39469633, 2024). "As a recognized cytosolic DNA sensor that activates anti-tumor immunity, cGAS has been less studied in its relationship with HPV proteins compared to IRF3 or STING." (PMID 39156107, 2024). "Given that previous studies have shown that NF-κB signaling pathway is crucial in tumor growth and drug resistance, we further explored the effect of the TRAF6/IRF3 axis on NF-κB-p65 in 5-FU-resistant GC cells, a key player in the NF-κB signaling pathway." (PMID 39706834, 2024). "In a word, the roles of IRF1, IRF2, and IRF3 in HCC are complex and bidirectional, exhibiting both tumor-promoting and anti-tumor effects." (PMID 39384770, 2024). "On the other hand, IRF3 suppresses Wnt/β-catenin to inhibit CRC tumorigenesis and IRF7 activation induces anti-tumor activity in CRC cells." (PMID 39384770, 2024). "Through the detection of proteins related to STING pathway in clinical tumor samples of CRC patients, we found that the levels of cGAS, STING, TBK1, IRF3 proteins and phosphorylation in CRC tissues all decreased." (PMID 39054486, 2024). "The precise mechanism responsible for the attenuation of the signaling pathway to IRF3 from cGAS/STING, despite the existence of cytoplasmic DNA in tumor cells, remains poorly understood." (PMID 38817608, 2024). "Targeted ADCs with wt Fc potently induced IRF3 reporter activity, which required ADC binding to both tumor antigen and FcγR, since minimal activity was observed with Fc-mutant and non-binding control ADCs." (PMID 38992037, 2024).
tumor (continued). "Interferon regulatory factor 3 (IRF3), which often suggests a poor prognosis for CRC patients, is an agonist of YAP1 and a target for tumor therapy." (PMID 39654621, 2024). "AAGd-NWs+RT-treated CT26 tumor cells significantly up-regulated the phosphorylation levels of STING and interferon regulatory Factor 3 (IRF-3) in the co-cultured cells." (PMID 38724527, 2024). "A STING-dependent adhesion and residency of TAMs in the tumor microenvironment was confirmed through genetic deletions of Zyxin, STING, and IRF3." (PMID 39304793, 2024). "Western blot results demonstrated that CISP significantly increased the expression of p-TBK1 and p-IRF3 in tumors, indicating that STING signal pathway in tumor sites was activated." (PMID 37607938, 2023). "Relying on the DNA-PK activation-dependent intrinsic immune response to IFN regulatory factor 3 (IRF-3), the combined DNA-PK inhibitors blocked DNA-PK pathway and decreased IRF-3 to promote the proliferation and expansion of OV M1 in tumor cells." (PMID 37040283, 2023). "Here, viral DNAs in the cytosol activated cGAS and downstream activated STING, IRF3, IRF7, IFN gene expression, and tumor death through the generation of antitumor CD8+ and CD4+ effectors in murine models." (PMID 38139802, 2023). "We also found that IRF1, IRF3, IRF4, IRF5 and IRF7 were significantly higher in tumor stage III/IV or grade 3/4 compared with tumor stage I/II or grade 1/2, whereas the expression level of IRF6 was lower in tumor stage III/IV or grade 3/4." (PMID 37182129, 2023). "The induction of STING pathway activates downstream IRF3 and TBK1 to drive the inflammatory cytokines and IFN-I production, thereby disrupting the immune tolerant status in tumor niches." (PMID 36879291, 2023). "Comparing gene expression of tumours to matched normal tissues, available only for TCGA LUAD and LUSC cancers, we observed a slight upregulation, on average, of IRF3 in both LUAD and LUSC (Pval = 7.111e-07 and 4.117e-06, respectively)." (PMID 35794238, 2022). "EBERs mediate inflammatory response through interferon regulatory factor 3 (IRF3) and NF-κB signaling pathways by targeting RIG-I, leading to tumor progression." (PMID 35311066, 2022). "2′,3′ -cGAMP, as a natural CDN, conducts its anti-tumor effect via notably boosting the expression of STING and IRF3." (PMID 35186921, 2022). "STING downregulation in SCLC tumours also correlates with a lower expression of cGAS/STING pathway-dependent genes, for both NF-kB- and IRF3-related responses." (PMID 35794238, 2022). "The involvement of DNA sensors in the antitumor response makes them attractive drug targets in tumor therapy, particularly for the cGAS-STING pathway and its downstream transcription factors IRF3 and NF-κB." (PMID 35983076, 2022). "We then investigated the protein expression of p-STING, p-IRF3 and p-TBK1 in tumor tissues from different treatment groups." (PMID 35386310, 2022). "Interferon regulatory factor-3 (IRF3), a transcription factor, plays an essential role in the induction of type I interferons that play an anti-tumor role." (PMID 35991835, 2022). "Particularly, in addition to the tumor immune escape pathway, genetic markers belonging to the cytokines/interleukins, including CXCL8, CCL5, CCR5 and angiogenic mediators including IGF1, IRF3, NOS2, appear to be the most promising." (PMID 36432658, 2022). "The incitement of IRF3 triggers the production of type I IFN and many other pro-inflammatory cytokines, which can activate CD8+ T cells to kill tumor cells." (PMID 35806118, 2022). "Further, IL-6 directly inhibits the IRF3/IFN-β arm of STING signaling in selected cancer cells, alleviating the tumor suppressive effects of the pathway in vivo." (PMID 35087822, 2021). "Altogether, we investigated the IRF family in CRC and revealed that the expression of IRF3 and IRF7 were related to tumor immune infiltration as well as prognosis of patients with CRC." (PMID 34488791, 2021).
tumor (continued). "On the contrary, relatively high level expression of PD-L1 in tumor and infiltrating immune cells is due to IFN-γ-mediated signaling via activation of IRF3." (PMID 33479394, 2021). "IRF3 activation in response to DDR promotes its role in upregulating RAE1, which is the tumor-cell ligand for NKG2D on NK cells." (PMID 34488791, 2021). "Specifically, IRF3, IRF7, and IRF9 were significantly upregulated in tumor tissues, whereas IRF4 was downregulated (P < 0.001)." (PMID 34488791, 2021). "Increased PD-L1 expression following treatment with DDR inhibitors is mainly IRF3-dependent, and tumor-growth inhibition and immune-checkpoint blockade with DDR inhibitors is completely dependent on the cGAS–STING–IRF3 axis." (PMID 34488791, 2021). "We also observed positive correlations between IRF3 and IRF7 protein expression levels and markers of tumor-infiltrating immune cell via IHC in 102 cases of CRC." (PMID 34488791, 2021). "By contrast, relatively high expression of PD-L1 in tumor and infiltrating immune cells correlated with IFN-γ production via IRF3 activation." (PMID 33479394, 2021). "Given that STING-TBK1-IRF3 signaling pathway is important for the production of type I IFNs and CD8+ T cell-mediated anti-tumor response, the expression of IRF3 in CRC was also analyzed in TCGA database." (PMID 31949493, 2020). "The enhanced expression of GADD153, IRF3 and IL-29 was also detected in the NGLY1-knockdown tumours." (PMID 30385822, 2018). "Transplantable mouse tumor model study showed defective T cell priming against tumor antigen in STING−/− and IRF3−/− mice." (PMID 29156566, 2017). "In vitro, IFN-β production and DC activation are triggered by tumor cell-derived DNA, via cyclic-GMP-AMP Synthase (cGAS), Stimulator of interferon genes (STING) and Interferon Regulatory Factor 3 (IRF3)." (PMID 27854240, 2016). "We observed here that radiation induces IRF3 and IFNβ, two key mediators of the STING pathway, in the tumor microenvironment." (PMID 27014915, 2016). "Tumor site analysis from immunofluorescence detection indicated that STING and IRF3 were significantly up-regulated upon cGAMP treatment." (PMID 26754564, 2016). "Through upstream regulator analysis it was predicted that several interferons, IFNγ, IFNα, IRF3, IRF7, and IFNA2, were up-regulated for spleens from old tumor bearing mice." (PMID 26497558, 2015). "The frequency of TLR3 expression in HCC tumor sections correlated positively with those of TRIF (γ = 0.322, P < 0.01), NF-κB (γ = 0.264, P < 0.05), and IRF3 (γ = 0.317, P < 0.01)." (PMID 25884709, 2015). "Then the influence of IRF-3 alternative splicing regulated by hnRNP A1/A2 and SF2/ASF on immunomodulatory functions of human tumor cells or immune cells justifies more extensive research." (PMID 23658645, 2013). "Positive rate of the IRF-3 protein in NSCLC tumor tissues (27/63, 42.9%) obviously increased in comparison with non-tumor tissues (5/39, 12.8%)." (PMID 23658645, 2013). "Notably, irradiated tumor cells, including CT26, H22, and GL261 cells, exhibited significantly increased phosphorylation levels of TBK‐1 and IRF‐3." (PMID 40470716, 2025). "Our findings revealed that Olaparib alone did not directly activate the p-STING/p-IRF3 axis or downstream anti-tumor activity in T cells." (PMID 40846839, 2025). "Furthermore, H-151 not only inhibited the p-STING/p-IRF3 axis but also significantly reduced the expression of T cell infiltration and activation markers (CD3D and CD69) as well as anti-tumor factors (GZMB, IFNγ, and TNFα)." (PMID 40846839, 2025). "Last, NK cells were also rescued in RTTPtgs1/2 KO tumours and in IRF3/7 overexpressing tumours, but NK cell depletion in Ptgs2 KO tumours did not significantly change the infiltration of cDCs and T cells or overall tumour control in our models." (PMID 39604727, 2025).
tumor (continued). "Meanwhile, PARPi activate the STING/TBK1/IRF3 pathway, resulting in increased expression of chemokines, such as the potent chemoattractants CXCL10 and CCL5, which target CD8+ T cells and enhance the immune response in the tumor microenvironment." (PMID 41460301, 2025). "Importantly, the deletion of RPS15AP12 diminishes the expression of RPS15A, leading to the upregulation of anti‐tumour immune responses by activating RIG‐I and MDA5 and downstream p‐TBK1 and p‐IRF3 as well as IFN‐β levels." (PMID 40000433, 2025). "Then, STING polymers recruit and activate TANK-binding kinase 1 (TBK1) which phosphorylates STING and interferon regulatory factor 3 (IRF3) and induces the production of IFN-Is and many other proinflammatory cytokines, regulating the natural anti-tumor-immune-responses in vivo." (PMID 40033359, 2025). "In endocrine-resistant ER+HER2- breast cancer, while hyperactivated AKT1 suppresses cGAS-STING signaling by binding to TBK1 and disrupting the TBK1/STING/IRF3 complex, combining AKT1 inhibitors with STING agonists restores innate immune activation and impairs tumor growth in preclinical models." (PMID 41573551, 2025). "To test whether re-establishment of a functional IFN-I pathway in RTT cancer cells is sufficient to restore responses to ACT, we overexpressed IRF3/7 in RTT cells and established tumours in Rag2–/– mice." (PMID 39604727, 2025). "This pathway primarily activates the IRF3/NF-κB signaling cascade upon recognition of cytosolic DNA, leading to the production of IFN-β, which subsequently promotes immune cell activation and tumor antigen presentation." (PMID 41357886, 2025). "In addition, SGLT2 inhibitors have been shown to activate the STING/IRF3/IFN-β axis in murine OS models, suppressing tumor growth and synergizing with 2′3′-cGAMP to enhance antitumor efficacy." (PMID 41415288, 2025). "Our findings indicated that DDX58, MAVS, C6orf150, IKBKE, TBK1, and IRF3 expression were not significantly correlated with tumor purity." (PMID 38817870, 2024). "Inhibition of TBK1, but not global IRF3 knockout, reduced tumor growth, F4/80+ macrophage infiltration, and pZyxin+ cells proportion." (PMID 39304793, 2024). "However, co-culture of ara-AMP or RT treated CT26 tumor cells with immune cells led to relatively weak STING and IRF-3 phosphorylation." (PMID 38724527, 2024). "Our results revealed that the promoter methylation levels of DDX58, MAVS, TMEM173, and IRF3 did not exhibit significant differences between normal and tumor samples." (PMID 38817870, 2024). "Together, the results indicate that tumor cell cytosolic detection of DNA by cGAS catalyzes the generation of 2′–5′ cyclic GMP‐AMP (cGAMP), which binds to STING, allowing it to recruit, phosphorylate, activate TBK1 and IRF3, and produce Type I IFNs." (PMID 37986544, 2023). "LID + US also significantly increased the percentage of CD80 + DC in the tumor, increased the percentage of CD86 + DC in the tumor-draining lymph nodes, and enhanced the phosphorylation of TBK1 and IRF3, which were related to the activation of STING pathway in the tumor tissue." (PMID 37391428, 2023). "STING then recruits TANK-binding kinase I (TBK1) which phosphorylates STING and interferon regulatory factor 3 (IRF3) which leads to the expression of type I IFNs to induce pro-inflammatory mediators and priming of CD8+ T cells in the tumor microenvironment (TME)." (PMID 37588093, 2023). "Recently, the author established the relationship between cytosolic IRF3 and Wnt/β-catenin signalling via AOM/DSS-induced chronic colonic inflammation mice models, demonstrating that IRF3 is a tumour suppressor, inhibiting Wnt signalling, instead of functioning as a transcription factor." (PMID 36766788, 2023). "Moreover, Mn2+ is a powerful cGAS activator to enhance STING-mediated type I IFN response in both tumor cells and DCs, involving STING, tank-binding kinase 1 (TBK1), and interferon regulatory factor 3 (IRF-3) phosphorylation 25,26." (PMID 37221157, 2023).
tumor (continued). "Therefore, we suggested that the level of IRF3, IRF6, IRF7, IRF8 and IRF9 were upregulated in tumor tissues of PC." (PMID 35012444, 2022). "Given the importance of tumor immunogenicity in the response to ICIs, TBK1 seems to play a central role since it contributes to innate immunity by activating interferon regulatory factor 3/7 (IRF3/7), thereby inducing type 1 interferon gene expression and supporting cell growth and self-renewal." (PMID 35406400, 2022). "Previously, we found that IRF3 and IRF7 could mediate the acquisition of new anti-tumor effector functions in macrophages." (PMID 34488791, 2021). "However, we detected a higher level of ki67+ cells per crypt in the distal colon, para-cancerous and tumor tissues from IRF3−/− mice and IRF3fl/flVillincre upon AOM treatment, or from the bone marrow chimaera mice IRF3+/+ → IRF3−/−." (PMID 33188184, 2020). "In irradiated groups, an approximately 2-fold increase in the number of tumor cells with IRF3 nuclear staining was detected compared to control nonirradiated cells (Ctrl group)." (PMID 33202881, 2020). "Tumor cell-derived DNAs can be detected by one of the major DNA sensors, cyclic GMP-AMP synthase (cGAS) (a cytosolic DNA sensor), which activates STING and then the TBK1 (the major kinase for IRF7 and IRF3 activation) pathway, thus inducing IFN-1 expression." (PMID 31049360, 2019). "Elevated IRF-3 protein expression was detected in NSCLC tumor tissues compared with non-tumor control tissues (42.9% vs. 12.8%, P = 0.001)." (PMID 23658645, 2013). "This supports the findings from human tumour cells where NS3/4A blocks the dsRNA-induced interferon response mediated by RIG-I, IPS-1 and IRF-3.3, 19, 23 Hence, these signalling events may now be studied in detail in vivo, albeit with care, using mouse models." (PMID 18689426, 2009). "This selective activation suggests targeting TLR3/TRAF3/IRF3 without activating NFκB could improve cancer immunotherapy by boosting anti-tumor immunity while minimizing immune suppression." (PMID 39949780, 2025). "DNA sensing is a ubiquitous innate immune pathway in both immune and tumor cells, initiated when cyclic GMP-AMP synthase (cGAS) detects cytosolic DNA and produces 2′3′-cyclic GMP-AMP (2′3′-cGAMP), which activates STING to trigger TBK1/IRF3-dependent IFN-β and ISG expression." (PMID 41148213, 2025). "The pathway exerts context-dependent effects: Antitumor: When the IRF3/IFN-I axis predominates, STING activation in dendritic cells potently primes CD8+ T-cell responses, transforming immunologically “cold” tumors into “hot” microenvironments conducive to tumor cell clearance." (PMID 41573551, 2025). "After radiation, Mn2+ is continuously released into tumor tissues to promote DC maturation by activating the cGAS-STING cascade signaling pathway, including inducing the phosphorylation of STING and interferon regulatory factor 3 (IRF3), and upregulating interferon beta (IFN-β) expression." (PMID 40585994, 2025). "We found that the expression levels of p‐STING, p‐TBK1, p‐IRF3, and p‐STAT1 were markedly increased in the Rfwd3 knockdown group compared to the shNC group, indicating that knocking down Rfwd3 in tumor cells results in activation of the STING pathway in adjacent immune cells." (PMID 41117130, 2025). "Given that IRF3 is a key component for recognition of tumor antigen during the innate immunity, this finding raises the possibility that NSD3 may play a critical role in tumor immune surveillance." (PMID 41301842, 2025). "Upon release inside the tumor microenvironment, these payloads activate the STING pathway in tumor and immune cells, triggering a signaling cascade that culminates in the phosphorylation of TBK1 and IRF3, resulting in robust type I interferon production and pro-inflammatory cytokine secretion." (PMID 40872592, 2025).